PIK3CA (phosphatidylinositol-4,5-bisphosphate 3-kinase catalytic subunit alpha)
Diseases named in the same sentence as PIK3CA in open-access papers (continued):
Sharing a sentence is not in itself a finding about the gene and the disease.
pancreatic cancer (57 papers, 2007 to 2026). "We reported that treatment with a PI3K inhibitor for pancreatic cancer with PIK3CA mutations complementarily enhanced the activation of ERK." (PMID 40638603, 2025). "We used a panel of pancreatic tumour cell lines generated by KRAS mutation combined with other genetic alterations including PIK3CA mutation and PTEN deletion (Dataset EV4A)." (PMID 34033220, 2021). "The salient finding of this study is that PIK3CA-AKT signaling regulates the susceptibility of KPC pancreatic tumors to T cell antitumor responses that result in infiltration and elimination of the tumor." (PMID 31112530, 2019). "Genetic ablation of Pik3ca counteracts these effects to render pancreatic tumors more immunogenic and thus more susceptible to T cell clearance." (PMID 31112530, 2019). "A second important phenotype caused by Pik3ca loss or AKT inhibition in pancreatic cancer cells is upregulation of CD80 on the cell surface." (PMID 31112530, 2019). "Activation of ERK1/2 signaling has been observed in other models with PIK3CA mutations including PIK3CA mutant breast and pancreatic cancers." (PMID 26863299, 2016). "Mutation occurrences in most genes had strong tendency toward mutual exclusivity, except for PIK3CA in colon, lung and pancreatic cancers that, on the opposite, tended toward co-occurrence: out of 67 PIK3CA mutations, 47 were co-occurring mutations (70%)." (PMID 26435479, 2015). "The identification of a subtype of pancreatic cancer initiated by PIK3CA mutations is an exciting advance as there is great potential for patients with cancers carrying these mutations to benefit from targeted therapies." (PMID 26436951, 2015). "This is hardly the case in KRAS downstream pathways, illustrated by the exceedingly low incidence of PIK3CA or BRAF mutations in pancreatic tumors." (PMID 24130864, 2013). "With respect to the PIK3CA mutational status, we identified one patient with a PIK3CA mutation (2%) in the samples tested, which is the frequency (3%) seen in pancreas cancer." (PMID 23342270, 2012). "In pancreas cancer, the frequency is low with approximately 3% of patients harboring a common PIK3CA mutation (542, 545, or 1047)." (PMID 23342270, 2012). "In pancreatic cancer a recent study described PIK3CA mutations in a fraction (11%) of the specimens analysed and some of the somatic mutations were novel." (PMID 19384426, 2007). "About 3–5 % of the patients with pancreatic cancer carry PIK3CA mutations." (PMID 39434498, 2025). "It is reported that PIK3CA mutations can lead to pancreatic tumor beginning." (PMID 29511477, 2017). "Future studies will need to further characterize the patient population with PIK3CA mutant pancreatic cancer, including assessment for concomitant mutations that may alter sensitivity to PI3K inhibition." (PMID 26436951, 2015). "Thus, we expected that the PIK3CA mutation is oncogenic for pancreatic cancer." (PMID 40638603, 2025). "In colorectal and pancreatic cancers, additional co-mutations in KRAS (non-G12C alleles), EGFR, PIK3CA, BRAF, and MAP2K1 are frequently detected at baseline and are linked to primary resistance, underscoring the importance of comprehensive NGS at diagnosis." (PMID 40940900, 2025). "These Pik3ca mutant pancreatic tumours were found to share morphological similarities with Kras mutant models, highlighting the significance of PI3 K signalling in the carcinogenic potential of pancreatic cancer." (PMID 39434498, 2025).
pancreatic cancer (continued). "Collectively, we observed EPLIN positively regulate protein expression several key proteins in MAPK and PIK3CA-AKT signalling in our pancreatic cancer cell modes." (PMID 39730634, 2024). "The driver mutations in the ctDNA of breast, colorectal, lung, and pancreatic cancers for the KRAS, PIK3CA, EGFR, and HER2 genes have been extensively studied by ddPCR assays." (PMID 37593116, 2023). "In a phase I basket study enrolling 166 patients with PIK3CA mutant solid tumours, taselisib showed limited activity (9% RR), with a partial response in a subset of pancreatic cancer patients (sarcomatoid and pseudopapillary)." (PMID 33546207, 2021). "Oncogenic KRASG12D signals through PIK3CA, but not PIK3CB, to induce acinar-to-ductal metaplasia that is required for pancreatic tumor formation, and the catalytic activity of PIK3CA is required for this tumorigenic process." (PMID 31112530, 2019). "To investigate the possible roles of Pik3ca and Egfr in pancreatic cancer progression, we used the FC1245 pancreatic cancer cell line that was isolated from a KrasLSL–G12D/+ Trp53LSL–R172H/+ Pdx1-Cre mouse in the C57BL/6 (B6) genetic background." (PMID 31112530, 2019). "Here we show using a syngeneic orthotopic implantation model of pancreatic cancer that Pik3ca regulates tumor immunogenicity." (PMID 31112530, 2019). "The differential sensitivity of pancreatic cancer cells to MEK inhibition can be attributed to the KRAS mutational subtype, copy number and the presence of PIK3CA co-mutation." (PMID 29435178, 2018). "Another group used digital PCR to detect alterations in KRAS, BRAF, and PIK3CA in pancreatic cancer patients, demonstrating that detection of any of these genes was associated with lower progression-free survival." (PMID 29137355, 2017). "PIK3CA mutations result in a constitutively active PI3K and are present in a subset of pancreatic cancers." (PMID 26436951, 2015). "As reported, growth of KRAS mutant pancreatic cancer cells with targeted inactivation of PIK3CA, a parallel branch of the KRAS signaling pathway, is also inhibited in syngeneic wild-type mice but not in nude mice due to the upregulation of MHC class I expression." (PMID 33674596, 2021). "Our results indicate that PIK3CA may be a potential drug target to increase T cell immunogenicity of pancreatic cancer." (PMID 31112530, 2019). "Interestingly, the Pik3ca mutant pancreatic cancers that develop in these models are morphologically indistinguishable from Kras mutant models and highly reminiscent of human cancers." (PMID 26436951, 2015). "Furthermore, TBL1XR1::PIK3CA fusions were detected in chordoma and pancreatic cancer." (PMID 41123735, 2025). "Hence, EPLIN might act as an important upstream regulator of MAPK and PIK3CA-AKT signalling events in pancreatic cancer." (PMID 39730634, 2024).
pancreatic cancer (continued). "Our recent study suggests that in contrast to MBC, the PI3K pathway could drive pancreatic cancer metastatic progression despite the absence of PIK3CA oncogenic mutations." (PMID 36765741, 2023). "As the table shows, its mRNA level also positively correlates with PIK3CA significantly (p = 0.0002), a crucial downstream effactor of KRAS in pancreatic cancer." (PMID 39730634, 2024). "The further novel funding of the TIMER database was that the expression level of FYN, MAPK, and PIK3CA correlate with immune infiltrates of B cell, CD8+ cell, macrophage, neutrophil, and dendritic cell in pancreatic cancer patients." (PMID 36091768, 2022). "Further, several molecular profiling studies revealed that up to 48% of pancreatic cancers harbor therapeutically relevant genomic alterations, such as ERBB2, MET, FGFR1, CDK6, PIK3R3, and PIK3CA at low individual patient prevalence." (PMID 35664782, 2022). "In conclusion, miR1425p acts as a tumor suppressor, inhibiting the migration and invasion of pancreatic cancer by inhibiting the expression of FAK and MMP9, as well as the signaling pathway phosphathydylositol/AKT 3-kinase by targeting PIK3CA." (PMID 34680441, 2021). "Our results indicate that tumor cell PIK3CA-AKT signaling limits T cell recognition and clearance of pancreatic cancer cells." (PMID 31112530, 2019). "Further studies are needed to identify the mechanisms downstream of PIK3CA and AKT that are responsible for downregulating MHC I and CD80 in pancreatic cancer cells." (PMID 31112530, 2019). "Several theoretically “actionable” aberrations exist in pancreatic cancer including, but not limited to, KRAS, CDKN2A, ARID1A, BRCA, PALB2, PIK3CA, BRAF and so forth." (PMID 25714017, 2015). "EGFR pathway genes, including, EGFR, KRAS, BRAF, and PIK3CA genes, are well-investigated oncogenes in many tumors including lung, colorectal (CRC), and pancreatic cancers (PAC)." (PMID 19826477, 2009). "Deleting PCCB in pancreatic tumor cells lacking PIK3CA leads to immune evasion, tumor progression, and ultimately, the death of the host animal." (PMID 40067762, 2025). "Thus, in the current study, we suggest that EPLIN acts as a putative oncogene in pancreatic cancer and a upstream regulator of MAPK and PIK3CA-AKT signalling events." (PMID 39730634, 2024). "In addition, the genes DUSP6, PIK3CA and YAP1 play critical roles in pancreatic cancer oncogenesis and tumor maintenance, which consequently impacts survival outcome." (PMID 30517129, 2018). "However, unlike ablation of Pik3ca in KPC tumor cells, all of the animals with downregulated PIK3CG eventually died from pancreatic cancer progression." (PMID 31112530, 2019).
hepatocellular carcinoma (53 papers, 2007 to 2026). A malignant tumor that arises from hepatocytes. "The combination of alpelisib, a selective PIK3CA inhibitor, with mTOR inhibitors has also shown a synergistic efficacy in PIK3CA-mutated (H1047R) hepatocellular carcinoma." (PMID 38344201, 2024). "PIK3CA mutations have been observed in various cancer types, including breast and hepatocellular carcinoma." (PMID 38675376, 2024). "Previous studies reported that PIK3CA mutation frequently occurred in breast and hepatocellular carcinomas." (PMID 25617745, 2015). "Six genes carrying DNVs were associated with human developmental disorders involving epithelial, connective or bone morphologies (PXDN, RTEL1, ANKRD11, MAP2K1, CYLD, ACAN) and four linked with cholangio- and hepatocellular carcinomas (PIK3CA, TLN1 CYLD, MAP2K1)." (PMID 27955658, 2016). "Several studies have shown that the dysregulation of the PI3K/Akt pathway is involved in cancer pathogenesis and prognosis, and PIK3CA gene mutations have been reported in several types of human cancers, including colorectal, breast and hepatocellular carcinomas." (PMID 22949056, 2012). "PIK3CA mutations are observed in a substantial subset of hepatocellular carcinoma (HCC) cases and are recognized as key drivers of tumor initiation and progression." (PMID 41133538, 2025). "Case presentation: In this paper we present a rare case of hepatocellular carcinoma with PIK3CA-positive and PYGO2-negative signaling pathways, several key aspects of the tumor’s behavior, prognosis, and treatment options." (PMID 41133538, 2025). "As has been reported, hsa-miR-192-5p plays a critical role in hepatocellular carcinoma by targeting multiple genes such as PIK3CA and AKT1." (PMID 41154714, 2025). "Five genes with de novo damaging alleles PIK3CA, TLN1 CYLD, and MAP2K1, are linked with cholangio- and hepatocellular carcinomas in addition to congenital syndromes and conditions related to tissue overgrowth." (PMID 27955658, 2016). "Lang reported that miR-124 suppresses cell proliferation in hepatocellular carcinoma by targeting PIK3CA." (PMID 23946636, 2013). "Conversely, we found PIK3CA mutation in only one SCC patient, confirming that, although frequent in breast, gastric and hepatocellular cancers, PIK3CA mutations are rare in NSCLCs." (PMID 22363436, 2012). "Another patient had hepatocellular carcinoma with PIK3CA H1047R and was treated at dose level." (PMID 27589687, 2016). "The treatment of hepatocellular carcinoma (HCC) is particularly challenging in cases with complex molecular profiles, such as PIK3CA-positivity and PYGO2-negativity, as observed here." (PMID 41133538, 2025). "In hepatocellular carcinoma (HCC), miR-124-3p directly targets PIK3CA to suppress tumor proliferation by attenuating PI3K-Akt signaling." (PMID 40625748, 2025). "In a case of hepatocellular carcinoma (HCC) which was PIK3CA-positive and PYGO2-negative, several key aspects of the tumor’s behavior, prognosis, and treatment options can be inferred." (PMID 41133538, 2025). "Somatic mutations of the PIK3CA gene, which encodes the p110alpha catalytic subunit of phosphatidylinositol 3-kinase (PI3K), are found across a range of cancers with the highest rates of mutation observed in breast, colon, endometrial, bladder and hepatocellular cancers (COSMIC data base)." (PMID 21303542, 2011). "Proteins in the first group, including AKT1, PIK3CA, MAPK3, MAPK2K1, and MAPK14, have been verified to be involved in the apoptosis of hepatocellular carcinoma cells." (PMID 36817123, 2023).
hepatocellular carcinoma (continued). "Circ-ZEB1 promotes phosphatidylinositol-4,5-bisphosphate 3-kinase catalytic subunit alpha (PIK3CA) expression by sponging miR-199a-3p, which affects the proliferation and apoptosis of hepatocellular carcinoma." (PMID 36609391, 2023). "The vast majority of the reported PTPN family members hold an inhibitory role in hepatocellular carcinoma (HCC), with the exception of PTPN11, which drives HCC progression by potentiating oncogenic proteins such as β-Catenin, PIK3CA and MET, and is associated with chemoresistance in HCC patients." (PMID 35957898, 2022). "Through miR-139/PIK3CA activated PI3k/Akt signaling pathway, LINC00152 accelerates tumorigenesis in hepatocellular carcinoma." (PMID 33088221, 2020).